ATF3 (activating transcription factor 3)
Diseases named in the same sentence as ATF3 in open-access papers (continued):
Sharing a sentence is not in itself a finding about the gene and the disease.
diabetes (24 papers, 2010 to 2025). "Research indicates that increased ATF3 expression leads to cell damage, including apoptosis of pancreatic β-cells, the generation of ROS, and high levels of glucose or FA associated with complications in diabetes." (PMID 38693581, 2024). "Meanwhile, this elevation in ATF3 is considered interesting; ATF3 has been previously reported to play a beneficial role in high-fat diet (HFD)-induced diabetes and pancreatic ß-cell dysfunction." (PMID 38044936, 2023). "Our findings showed, for the first time, that excessive AGEs and copper in diabetes upregulated ATF3/SPI1/SLC31A1 signaling, thereby disturbing copper homeostasis and promoting cuproptosis." (PMID 36675183, 2023). "The excessive increase in AGEs and copper in diabetes induced the upregulation of copper importer SLC31A1 through ATF3/SPI1, thereby mediating the accumulation of copper in cardiomyocytes, disturbing copper homeostasis and promoting cuproptosis." (PMID 36675183, 2023). "In diabetes, ATF3 also promoted β-cell dysfunction, accelerated STZ- induced diabetic liver injury and aggravated podocyte injury of db/db mice." (PMID 36675183, 2023). "Another four TFs (JUN, EGR1, NR1D1, and ATF3) (in italic) were almost involved in all the diabetes-related term and pathways." (PMID 36050744, 2022). "ATF3 is reportedly involved in the pathogenesis of diabetes and its complications through its transcription factor activity in response to oxidative stress." (PMID 36340581, 2022). "In contrast, ATF3 is shown to play a beneficial role by enhancing glucose tolerance in high-fat diet-induced diabetes and pancreatic β cells dysfunction." (PMID 35216322, 2022). "STZ treatment increases the expression of interferon-γ (IFNγ) and STAT1 in diabetic liver injury, which is accompanied by upregulated hepatic ATF3 expression." (PMID 32922364, 2020). "ATF3 overexpression in sensory neurons has also been shown in experimental models of cisplatin, paclitaxel and diabetes-induced PN." (PMID 24069168, 2013). "Additionally, in high-glucose conditions mimicking in vivo diabetes, mesangial cells exhibited increased nuclear translocation of NF-κB (phosphorylated p65), which was reduced by ST32da-induced Atf3 expression." (PMID 41369384, 2025). "ATF3 has been shown to be involved in many pathological conditions such as cancer, infections/inflammation, diabetes, and ischemic injury of hearts, livers, or brains, highlighting the importance of understanding the exact role of ATF3 in the cellular stress response." (PMID 31273299, 2020). "• The stress factor ATF3 is induced in podocytes from proteinuric patients, including diabetes." (PMID 29038896, 2018). "Thus, the number of cleaved caspase 3 stained cells seems to balance the number of ATF3 stained cells at the lesion site in various models of diabetes and in healthy rats." (PMID 25216784, 2014). "The potential link between ATF3 and diabetes pathway as found in our study is consistent with a recent study showing that ATF3 activated in obese adipose cells contribute to insulin resistance through down-regulation of adiponectin and a glucose transporter GLUT4." (PMID 22046379, 2011). "Our data indicated that ATF3 and/or SPI1 might be upstream of SLC31A1 and regulate cuproptosis of cardiomyocytes in diabetes." (PMID 36675183, 2023).
diabetes (continued). "For example, ATF3 induction by proinflammatory cytokines and glucose is partially mediated by the NF-κB and JNK/stress-activated protein kinase (SAPK) signaling pathways, which are two stress-induced pathways involved in inflammatory responses and diabetes." (PMID 36472556, 2023). "We identified 8 hub genes (JUN, ATF3, VEGFA, SLC2A1, HK2, PTGS2, PFKFB3, and KLF6) that were enriched in response to hypoxia, angiogenesis, vasculogenesis, hypoxia-induced signaling, cancer, diabetes, and transplant-related disease pathways." (PMID 36482897, 2022). "Notably, a pro-apoptotic role for ATF3 in beta cells was originally assumed, and ATF3−/− mice were predicted to be protected in a T2D model of HFD-induced diabetes." (PMID 35326476, 2022). "ATF3 induction is partially mediated by the NF-κB and JNK/stress-activated protein kinase (SAPK) signaling pathways, which are two stress-induced pathways involved in diabetes." (PMID 32922364, 2020). "Taken together, these data indicate that metabolic pathways, cell cycle, apoptosis, and insulin and VEGF signalling are unique targets of stress-induced ATF3, whereas diabetes mellitus and calcium signalling, but not cell cycle and apoptosis, are unique targets of ATF3 expressed in cancer cells." (PMID 22046379, 2011).
gastric cancer (21 papers, 2013 to 2025). A primary or metastatic malignant neoplasm involving the stomach. "Similarly, ATF3 is implicated in ferroptosis induction via inhibition of the Nrf2/Keap1/xCT pathway, which enhances cisplatin sensitivity in gastric cancer cells." (PMID 40115255, 2025). "Subsequently, activation of the Nrf2/Keap1 pathway may relieve the inhibition of ATF3 in gastric cancer cells, indicating that ATF3 is likely to cause ferroptosis through Nrf2 to imbalance the antioxidant system in gastric cancer cells." (PMID 40959280, 2025). "In EBV-associated gastric cancer (EBVaGC), EBV-EBNA1 can promote ATF3 expression by binding to the enhancer region upstream of ATF3." (PMID 39056735, 2024). "In cisplatin-resistant gastric cancer, elevated ATF3 expression cooperates with erastin to inhibit the Keap1-Nrf2-xCT pathway, thereby promoting ferroptosis in cancer cells and reversing cisplatin resistance." (PMID 39744125, 2024). "In a study of gastric cancer (GC), activating transcription factor 3 (ATF3) inhibited the activity of CEMIP promoter." (PMID 37662915, 2023). "Ferroptosis is induced by the elevated level of activating transcription factor 3 (ATF3) inhibiting the Nrf2/KEAP1/SLC7A11 signaling pathway in gastric cancer cells, which alleviates cisplatin resistance." (PMID 37833746, 2023). "Low ATF3 expression was correlated to shorter survival and poorer prognosis in gastric cancer patients." (PMID 35631574, 2022). "Guohua Xie and co-workers at Shanghai Jiao Tong University, China, explored the function of ATF3 in human gastric cancer tissues." (PMID 34728784, 2021). "ATF3 (activating transcription factor 3) may induce ferroptosis by blocking the Nrf2/Keap1/xCT signaling pathway and reverse the sensitivity of gastric cancer cells to cisplatin." (PMID 35847022, 2022). "Reduced ATF3 expression also boosted the invasiveness of gastric cancer cells." (PMID 34728784, 2021). "When the ATF3 expression is expressed at lower levels in some cancers, such as esophageal squamous cell carcinoma and gastric cancer, ATF3 may act as a tumor suppressor." (PMID 28402947, 2017). "Notably, ATF3 inhibits the growth of gastric cancer cells and relieves their resistance to cisplatin; further its expression level is closely related to the prognosis of patients with gastric cancer." (PMID 40959280, 2025). "However, the mechanisms underlying the abnormal expression of ATF3 and its biological function in gastric cancer (GC) have not been well investigated." (PMID 34728784, 2021). "Initial results suggest that overexpression of ATF3 could suppress gastric cancer progression." (PMID 34728784, 2021). "Further, the activating transcription factor 3 gene (ATF3) is thought to influence tumorigenesis, although its role in gastric cancer is unclear." (PMID 34728784, 2021). "Furthermore, upregulation of ATF3 can downregulate the transcription of GPX4, promote ferroptosis, and inhibit the proliferation of gastric cancer cells, providing a potential therapeutic target for gastric cancer." (PMID 41550926, 2025). "Moreover, ATF3 may block the NRF2/Keap1/xCT signaling pathway, which makes gastric cancer cells sensitive to ferroptosis." (PMID 39056735, 2024).
Hepatic steatosis (20 papers, 2012 to 2025). Steatosis is a term used to denote lipid accumulation within hepatocytes. "Given that TNFα leads to RIPK3 activation and necroptosis induction, which increases inflammation and TNFα levels, ATF3-dependent induction of RIPK3 in severe hepatic steatosis can cause a vicious cycle of necroptosis and inflammation." (PMID 36690638, 2023). "In severe hepatic steatosis, after partial hepatectomy, hepatic ATF3-deficient or -overexpressing mice display decreased or increased RIPK3 expression and necroptosis, respectively." (PMID 36690638, 2023). "A key finding of this study is that NMN therapy significantly reduces Atf3, which has been linked with hepatic steatosis, oxidative stress, mitochondrial function, and ethanol-induced metabolic syndrome." (PMID 31823815, 2019). "Furthermore, a recent report demonstrated that increased Atf3 expression was associated with hepatic steatosis and Atf3 is one of many transcription factors that have been found to be upregulated in patients with alcoholic steatohepatitis." (PMID 31823815, 2019). "We also revealed that this ATF3-dependent RIPK3 induction plays an important role in the pathogenesis not only of post-hepatectomy acute liver damage in hepatic steatosis but also of chronic liver damage in MCD-fed NASH mice and in patients with NASH." (PMID 36690638, 2023). "To elucidate the mechanism of ATF3 induction after hepatectomy in severe hepatic steatosis, we performed hepatic overexpression of mouse GADD34, a phosphatase of eIF2α." (PMID 36690638, 2023). "We found that the mode of hepatocellular death shifts from apoptosis to necroptosis as the hepatic steatosis is exacerbated and that the eIF2α signalling-inducing transcription factor ATF3 determines this modal shift through RIPK3 induction." (PMID 36690638, 2023). "An animal study reported that increased hepatic activating transcription factor 3 levels play an important role in hepatic steatosis, IR, and subsequent type 2 DM." (PMID 34516586, 2021). "ATF3 KO mice reveal hepatic steatosis and manifest the expansion of G-MDSCs in the liver and numerous immune organs." (PMID 32922364, 2020). "ATF3 is involved in host immunity against pathogens and some specific inflammatory diseases, such as hepatic steatosis, asthma, and colitis." (PMID 32922364, 2020). "Activating transcription factor 3 (ATF3)/S100A9 signalling plays an important role in GC‐mediated G‐MDSC accumulation in the fatty liver disease." (PMID 33094923, 2020). "A recent report demonstrated that Atf3 played a key role in oxidative stress-mediated hepatic steatosis and that Atf3 silencing reduced ALT levels." (PMID 31823815, 2019). "ATF3 knockdown in Zucker diabetic fatty rats also ameliorates hepatic steatosis by restoring FAO." (PMID 39911797, 2025). "Our results demonstrated that E6446 could significantly suppress SCD1 activity, inhibit hepatic lipogenesis and adipogenic differentiation and improve HFD-induced hepatic steatosis via the target liver-adipose axis in an ATF3 dependent manner." (PMID 37777801, 2023). "ATF3 is overexpressed in fatty liver and may play an essential role in the occurrence and development of oxidative stress-mediated hepatic steatosis, and ATF3 silencing in vivo may be a potentially important target for the prevention of NAFLD." (PMID 36380355, 2022). "However, other studies have suggested that ATF3 promotes hepatic steatosis." (PMID 39911797, 2025). "By decreasing ATF3, cardiolipin synthase 1 (CRLS1), a member of the cytidine diphosphate-alcohol phosphatidyl transferase class-I family, decreases insulin resistance, hepatic steatosis, inflammation, and fibrosis." (PMID 39911797, 2025). "Both ATF3 and RIPK3 expression are low before hepatectomy in HFD-fed mice, even with severe hepatic steatosis induced by 16 weeks of feeding." (PMID 36690638, 2023).
Hepatic steatosis (continued). "By reducing the expression and activity of ATF3, CRLS1 reduces insulin resistance, hepatic steatosis, inflammation, and fibrosis during the pathological phase of non-alcoholic steatohepatitis (NASH)." (PMID 35677823, 2022). "Indeed, inhibition of the eIF2α signalling pathway by overexpression of GADD34, a phosphatase of eIF2α, decreased the expression of ATF3 and RIPK3 after resection of severe hepatic steatosis." (PMID 36690638, 2023). "While ATF3 is the inducer of RIPK3, TNFα is a vital activator of RIPK3 in hepatic steatosis." (PMID 36690638, 2023). "Next, we induced hepatocellular ATF3 overexpression in mice with severe hepatic steatosis without hepatectomy to examine the role of ATF3 in RIPK3 expression and necroptosis." (PMID 36690638, 2023). "TNFα neutralisation decreased c-Jun phosphorylation, but not ATF3 expression, after hepatectomy in HFD-induced severe hepatic steatosis, indicating that JNK-c-Jun signalling may have an insignificant effect on ATF3 induction in this model." (PMID 36690638, 2023). "In this study, we elucidated that ATF3 is the inducer of RIPK3, but not the activator, and the determinant of the modal shift from apoptosis to necroptosis in severe hepatic steatosis." (PMID 36690638, 2023).
glioblastoma (18 papers, 2015 to 2025). The most malignant astrocytic tumor (WHO grade IV). "The fourth cell line, GBM1 from Glioblastoma multiforme, is an aggressive brain cancer, wherein ATF3 is a tumor suppressor and its loss of function is indicative of high-grade cancer and poor prognosis." (PMID 28186491, 2017). "Brucine has been shown to upregulate activating transcription factor 3 (ATF3), leading to apoptosis in glioblastoma cell lines." (PMID 40286187, 2025). "Gene expression of klf6 is significantly upregulated by overexpression of ATF3 in glioblastoma cells." (PMID 28250971, 2017). "Our study for the first time identifies ATF3 as a potential novel therapeutic target in glioblastoma." (PMID 28250971, 2017). "For example, at an FPR-cutoff of 0.10, in the Glioblastoma cell line, the ATF3 homodimer classified just 39% of the ATF3 ChIP-seq peaks as positive, whereas 85% of the peaks are classified positive by at least one of the ATF3-containing dimers at FPR 0.10." (PMID 28186491, 2017). "In this study, the inhibitory effects of ATF3-siRNA were observed in the human glioblastoma cell line, U373MG, in vitro and in tumor xenografts in vivo." (PMID 25872784, 2015). "Over the last few years, many studies have aroused an interest in activating transcription factor 3 (ATF3) as a novel tumor suppressor mediator in glioblastoma, as well as colon, lung, bladder, and cervical cancer cells and its possible therapeutic applications." (PMID 36522783, 2022). "This highlights the considerable importance of research into ATF3 in glioblastoma." (PMID 28250971, 2017). "The transfection of U373MG glioblastoma cells with ATF3-siRNA induced a number of changes in cell behavior; the cell proliferative activity was decreased and flow cytometry revealed an increased proportion of cells arrested in the G0/G1 phase of the cell cycle." (PMID 25872784, 2015). "Therefore, we propose that ATF3 could serve as prognostic marker for migration and metastatic disease in glioblastoma." (PMID 28250971, 2017). "Therefore we chose migration for further investigation of the role of ATF3 in glioblastoma." (PMID 28250971, 2017). "Several studies have demonstrated that alterations in NO production regulates ATF3 expression and consequently interferes in MMP-2 expression in endothelial cells, glioblastoma, and mouse brain endothelial cells." (PMID 35137850, 2022). "ATF3 and c-JUN act downstream of GADD45α to mediate the stress-related pathway in glioblastoma cells." (PMID 31541175, 2019). "MMP and TIMP genes have been shown to regulate cancer cell invasion, and ATF3 is reported to reduce the ability to migrate by regulating the MMP and TIMP expression in human glioblastoma cells." (PMID 29966001, 2018). "Interference with ATF3-levels protected cells from apoptosis induction, e.g. induced by TNFα in HUVEC, by cisplatin in a human glioblastoma cell line, or related to doxorubicin in cardiomyocytes." (PMID 25590623, 2015). "In addition, we demonstrate a positive correlation between ATF3 and phosphorylation of STAT3 and the inhibition of nuclear translocation of NFκB in glioblastoma cells." (PMID 28250971, 2017). "The reason for this difference in results may be that under in vitro conditions, human glioblastoma U373MG cells were more sensitive to cisplatin and ATF3-siRNA + cisplatin." (PMID 25872784, 2015). "P4HA1, an enzyme involved in collagen hydroxylation and hypoxia response, has been recently shown to regulate succinylation in glioblastoma by increasing intracellular succinate and enhancing PGK1 K191/K192 succinylation, which stabilizes PGK1 and promotes aerobic glycolysis via the HIF1α/ATF3 axis." (PMID 40463370, 2025). "Stress-inducible genes, such as GADD45α/β, ATF3, and c-JUN, which were remarkably upregulated in PAM-treated glioblastoma cells, were not upregulated by PAL." (PMID 31541175, 2019).